NRG1 (neuregulin 1)
Diseases named in the same sentence as NRG1 in open-access papers (continued):
Sharing a sentence is not in itself a finding about the gene and the disease.
gastric cancer (18 papers, 2009 to 2025). A primary or metastatic malignant neoplasm involving the stomach. "In gastric cancer tissues, NRG1 is overexpressed, which is closely associated with aggressive clinicopathological parameters such as larger tumor size, invasive growth, and lymph node metastasis." (PMID 41378303, 2025). "The overexpression of NRG1 in stromal cells and cancer cells was observed in tumor tissues of gastric cancer patients and was associated with clinical stage lymph node metastasis and survival in gastric cancer patients." (PMID 28350359, 2017). "In gastric cancer, NRG1 associates with its receptors, HER3 and HER4, might be an independent and unfavorable prognostic factor and a therapeutic target." (PMID 29535422, 2018). "CASC9 expresses highly by miR-125b/neuregulin-1 in hemangioma, colon, lung, and gastric cancers, etc.." (PMID 35427373, 2022). "NRG1 and CARD11 were reported to be recurrently mutated in gastric cancer and B-cell lymphoma, respectively." (PMID 26109429, 2015). "Furthermore, NRG1 can activate the NF-κB-signaling pathway to promote the self-renewal of gastric cancer stem cells, indicating that NRG1 overexpression predicts an unfavorable prognosis in gastric cancer patients." (PMID 41378303, 2025). "miR-200b targets Neuregulin 1 (NRG1) to inhibit the invasion of gastric cancer cells." (PMID 35682560, 2022). "Interestingly, relatively high NRG1 expression was also observed in a number of HER2+ gastric cancer tumors and one breast cancer tumor, suggesting that these tumors may exhibit both ligand-dependent and ligand-independent activation of HER3." (PMID 28899363, 2017).
Stroke (17 papers, 2016 to 2026). Sudden impairment of blood flow to a part of the brain due to occlusion or rupture of an artery to the brain. "The objective of this cross-sectional study was to measure plasma NRG-1 in children with SCA and determine if NRG-1 levels are correlated with severity of hemolysis or known biomarkers of stroke risk in SCA, PDGF-AA and BDNF." (PMID 35935682, 2021). "Here, we investigated the role of this signaling pathway in neuroprotection and we now provide evidence that Nrg1 intracellular signaling can alleviate neuronal loss upon stroke in cortical neurons." (PMID 31583038, 2019). "ETS-1 was identified as a candidate transcription factor associated with the regulation of gene expression by stroke and NRG1 treatment." (PMID 29856744, 2018). "What our data suggest is that stroke causes transcriptional activation via the NF-kB p65-binding site, and NRG-1 prevents the binding of p65 to the TFBS by sequestering it in the cytoplasm." (PMID 27596278, 2016). "The Conserved Transcription Factor-Binding Site Finder (CONFAC) bioinformatics software package was used to predict transcription factors associated with inflammatory genes induced following stroke and suppressed by NRG-1 treatment." (PMID 27596278, 2016). "Together with other blood biomarkers of stroke risk, NRG-1 may be a useful diagnostic test for impaired cerebral perfusion." (PMID 35935682, 2021). "In addition, studies have implicated Nrg1 in pathologies such as neuroinflammation, neurodegenerative disorders, and stroke." (PMID 31583038, 2019). "Previous studies suggested that Nrg1 forward signaling via ErbB4 may aid recovery from stroke, a pathology associated with aging in humans." (PMID 31583038, 2019). "Gene ontology ID and biological processes associated with genes altered following stroke and NRG1." (PMID 29856744, 2018). "Neuroprotection in stroke by NRG-1 is mediated by erbB4 which physically associates with NIK." (PMID 27596278, 2016). "Neuregulin-1 (NRG-1) has shown potent neuroprotective and anti-inflammatory properties in preclinical stroke models, with evidence of enhanced neuronal regeneration when administered after injury." (PMID 42311785, 2026). "The results support further development of NRG-1 as a clinically translatable, multimodal therapy for extending the post-stroke treatment window and promoting functional recovery." (PMID 42311785, 2026). "NRG-1 prevented macrophage/microglial activation, reactive astrogliosis, apoptosis, and cytokine expression following stroke." (PMID 38638304, 2024). "Similar results were shown with erbB4 knockout mice following stroke where neuroprotection by NRG-1 against cerebral ischemia was prevented in the mice with erbB4 deleted in parvalbumin (PV)-positive interneurons." (PMID 38638304, 2024). "NRG-1 significantly reduced ischemia-induced neuronal death, neuroinflammation and oxidative stress in rodent stroke models with a therapeutic window of >13 h." (PMID 38638304, 2024). "We and others have demonstrated the clinical potential for neuregulin-1 (NRG-1) in preclinical stroke studies." (PMID 38638304, 2024). "This review summarizes previous stroke clinical candidates and provides evidence that NRG-1 represents a novel, safe, neuroprotective strategy that has potential therapeutic value in treating individuals after acute ischemic stroke." (PMID 38638304, 2024). "Plasma NRG-1 was also positively correlated with elevations in both PDGF-AA and BDNF, previously reported biomarkers of high stroke risk in children with SCA." (PMID 35935682, 2021). "In conclusion, our work establishes a novel role for intracellular Nrg1 signaling in neuroprotection upon stroke in vitro and in vivo." (PMID 31583038, 2019). "Administration of NRG1-AdMSCs resulted in significant improvement of functional outcome following stroke compared to AdMSCs- or adenoviral NRG1-treated group, in addition to the reduction in the infarct size evaluated by hematoxylin and eosin staining." (PMID 31560696, 2019).
Stroke (continued). "Taken together, the data gathered from this in vitro model suggest a neuroprotective role of Nrg1 intracellular signaling upon stroke." (PMID 31583038, 2019). "CONFAC compared our gene list to seven random control datasets to identify statistically over-represented TFBS in genes altered by stroke and reversed by NRG-1." (PMID 27596278, 2016). "In a number of other CNS disorders (such as stroke), Nrg1 has been shown to haveneuroprotective effects (Croslan etal., 2008; Iaci etal., 2010)." (PMID 26993800, 2016). "Our findings suggest that peripheral macrophages are a source of Neuregulin-1 post-stroke." (PMID 40537024, 2025). "Future studies utilizing the Townes mouse model of SCA may provide clearer insights as to the neuroprotective role of NRG-1 in SCA associated cerebral injury and stroke." (PMID 35935682, 2021). "Moreover, multiple brain diseases including multiple sclerosis, traumatic brain injury, and stroke can enhance NRG1-ErbB signaling networks." (PMID 31560696, 2019). "Given previous studies that implicate Nrg1 in age-related diseases such as neuroinflammation, neurodegeneration, and stroke, we assessed whether the decreased expression of Nrg1 might indicate a role of Nrg1 in neuroprotection." (PMID 31583038, 2019). "Here, we investigated the role of Nrg1 intracellular signaling in neuroprotection and stroke." (PMID 31583038, 2019). "Thus, we provoked stroke in an area adjacent to the region previously infected to express Nrg1-ICD or GFP as control." (PMID 31583038, 2019). "In accordance with prior reports, our NRG1-expressing AdMSCs, which was confirmed to release high levels of NRG1, could result in improved post-stroke motor function." (PMID 31560696, 2019). "As the involvement of Nrg1 intracellular signaling in stroke remains unaddressed, we assessed whether Nrg1 intracellular signaling could be neuroprotective in stroke." (PMID 31583038, 2019). "Taken together, these findings suggest that NRG-1 may be a potential therapeutic treatment for treating stroke and other neuroinflammatory disorders." (PMID 27596278, 2016). "Finally, we investigated the relevance of Nrg1 intracellular signaling in stroke in vivo." (PMID 31583038, 2019). "We next tested the hypothesis that Nrg1 intracellular signaling may be involved in stroke." (PMID 31583038, 2019). "As previous studies indicated an increase in Nrg1 expression in response to hypoxia and that ErbB4 activation reduced ischemic infarct, we hypothesized that Nrg1 intracellular signaling might be neuroprotective in hypoxia and stroke." (PMID 31583038, 2019). "Hence, we tested the hypothesis that Nrg1 intracellular signaling could be neuroprotective in stroke." (PMID 31583038, 2019). "Given the complexity of the neurotoxic effects of stroke and the involvement of various mechanisms, such as the generation of ROS, excitotoxicity, and inflammation, further studies are required to determine the molecular bases of the neuroprotective effect of Nrg1 intracellular signaling." (PMID 31583038, 2019). "Therefore, understanding the mechanisms used by NRG1 to prevent neuronal cell death could lead to the development of a novel strategy to treat stroke." (PMID 29856744, 2018). "Astragaloside VI (2 μg/kg, 100 nM) miligated post-stroke depression by increasing DA and 5-HT release through upregulation of the MEK/ERK pathway mediated by the neurotrophic factor neuregulin 1 (NRG-1)." (PMID 37654609, 2023). "In our cross-sectional study, we are unable to determine the trend of NRG-1, BDNF, PDGF-AA, versus cerebral arteriopathy or progression to stroke over time for these subjects." (PMID 35935682, 2021). "In addition, as NRG1 could suppress stroke-induced pro-inflammatory and stress-related gene expressions, which are related with the molecular mechanisms of MSCs in ischemic stroke, NRG1 can be an attractive target for MSCs modification to maximize therapeutic efficacies of cell-based therapy." (PMID 31560696, 2019).
Stroke (continued). "We discovered that Nrg1 expression significantly increased neuronal survival upon oxygen-glucose deprivation (OGD), an established in vitro model for stroke." (PMID 31583038, 2019). "The identification of genes affected by NRG-1 treatment and the transcription regulators modulating these genes will provide important insight into the mechanism of NRG-1 protection following stroke." (PMID 29856744, 2018). "We developed a novel non-human primate MCAO stroke model in Rhesus macaques that will be used to examine the efficacy of NRG-1 in a gyrencephalic species using MRI, histology, neurobehavioral and other studies." (PMID 38638304, 2024). "Interestingly, previous studies suggested a role for Nrg1 in stroke: Nrg1 expression increased upon stroke and the administration of the Nrg1-EGF domain alleviated experimental stroke." (PMID 31583038, 2019). "With regard to a potential mechanism, in both models, we found that the stroke-induced Aβ and tau deposits co-localized with increased levels of β-secretase 1 (BACE1), along with its substrate, neuregulin 1 (NGR1) type III, both of which are proteins integral for myelin repair." (PMID 30249297, 2018). "In the lower group (NRG-1 < 122.5 pg/ml), MACCEs were reported in 30 patients, which included 7 individuals hospitalized due to HF, 20 patients with ACS, 1 patient with severe arrhythmia, 1 patient with stroke, and 1 patient who experienced sudden cardiac death." (PMID 40747492, 2025).
Hirschsprung disease (16 papers, 2011 to 2024). Hirschsprung disease (HSCR) is a congenital intestinal motility disorder that is characterized by signs of intestinal obstruction due to the presence of an aganglionic segment of variable extent in the terminal part of the colon. "Although research on intestinal diseases is limited, genetic variations located at the NRG1 have been found to increase the risk of congenital megacolon." (PMID 38433839, 2024). "Common variants in RET and NRG1 have been associated with Hirschsprung disease (HSCR), a congenital disorder characterised by incomplete innervation of distal gut, in East Asian (EA) populations." (PMID 36443333, 2022). "RET, NRG1, and L1CAM genes are reported as pathological gene variants associated with the incidence of different variants of Hirschsprung's disease." (PMID 38169757, 2023). "In turn, observations conducted on humans have indicated that NRG1 is involved in pathological processes connected with intestinal diseases resulting from incorrect organization of the enteric ganglia, including Hirschsprung’s disease and diverticular disease." (PMID 33228092, 2020). "Through a genome-wide association study (GWAS) on Chinese individuals we identified the association of a 350 kb genomic region encompassing intron 1 of the NRG1 gene with Hirschsprung's disease." (PMID 21283760, 2011). "NRG1 gene was considered as an important signature of Hirschsprung disease." (PMID 35321516, 2022). "Moreover, it is known that disturbances of NRG1 expression in the intestinal nervous structures occur during gastrointestinal diseases, including diventricular disease and Hirschsprung’s disease." (PMID 33228092, 2020). "Substantial resources have been devoted to evaluate the relationship between NRG1 variants rs7835688 and rs16879552 and Hirschsprung’s Disease (HSCR) but no consistency exists." (PMID 28855726, 2017). "Besides Hirschsprung’s disease, NRG-1 may also take part in other intestinal pathological states characterized by atrophy of enteric nervous structures, including diverticulosis, slow-transit constipation, or gastrointestinal neuromuscular diseases." (PMID 30274171, 2018). "In this project, we performed an exploratory analysis to look for statistical epistasis in two Hirschsprung disease related regions of the genome—the TADs encompassing the RET and NRG1 genes." (PMID 36443333, 2022). "studies indicate that NRG1 is involved in Hirschsprung's disease that is a congenital disorder with the absence of enteric ganglia in variable portions of the distal intestine." (PMID 33585010, 2020).
Cerebral ischemia (15 papers, 2016 to 2025). Restriction of arterial blood supply to the brain associated with insufficient oxygenation to support the metabolic requirements of the tissue. "This has been observed in cases of brain injury due to trauma or cerebral ischemia, where there is an increase in the local expression of NRG1 in the brain, in an attempt to induce a protective response against brain injury." (PMID 35625715, 2022). "Conversely, it has been shown that reduction of endogenous NRG-1, as observed in NRG-1 +/− mice, results in exacerbated neuronal injury following induced cerebral ischemia." (PMID 35935682, 2021). "Our data are intriguing in that some subjects without known cerebral arteriopathy have elevations of neuroprotective proteins, BDNF and NRG-1, suggesting a response to subclinical cerebral ischemia in children with SCA." (PMID 35935682, 2021). "Previous studies demonstrated that the soluble EGF domain of Nrg1 alleviated brain ischemia, a pathological process involving the generation of free radicals, reactive oxygen species (ROS), and excitotoxicity." (PMID 31583038, 2019). "According to the previous studies, the expression of NRG1 and ErbB4 receptors significantly increased in the acute phase in cerebral ischemia (24 h after surgery) and in traumatic brain injury." (PMID 29875654, 2018). "In recent years, Neuregulin-1 has exhibited promising neuroprotective effects in cerebral ischemia." (PMID 40537024, 2025). "CIGs mitigate neuroinflammation in autoimmune encephalitis and traumatic brain injury by inhibiting the JAK/STAT and NF-κB/STAT3 pathways, while protecting against white matter lesions in rat models of cerebral ischemia through activation of the BDNF/Neuregulin-1 pathway." (PMID 41403435, 2025). "In addition, the underlying mechanism of EBP-bFGF/ECM was explored by transcriptome analysis and the neuroprotective NRG1/AKT signaling pathway involved in the repair of cerebral ischemia." (PMID 38715911, 2024). "Because NRG-1 has shown to be protective against cerebral and cerebrovascular injury in a number of models, elevated NRG-1 production in children with SCA may represent an endogenous response to subclinical reduced cerebral ischemia." (PMID 35935682, 2021). "Because people with SCA may experience cerebral ischemia and heme-mediated vascular injury, it is likely that NRG-1 plays a role in the brain and cerebral vasculature in SCA." (PMID 35935682, 2021). "We hypothesized that NRG-1, being neuroprotective, would be increased in children with SCA in response to either hemolysis or cerebral ischemia (Kassim and DeBaun, 2013, Talmage, 2008)." (PMID 35935682, 2021). "In addition, NRG1 is known to exert neuroprotection through ErbB4 receptor in MPTP models of Parkinson’s disease and cerebral ischemia." (PMID 26891847, 2016).
colorectal cancer (14 papers, 2015 to 2025). A primary or metastatic malignant neoplasm that affects the colon or rectum. "Our study identified NRG1 as a methylation-linked biomarker with predicted phase-separation propensity in colorectal cancer." (PMID 41190067, 2025). "Analysis of transcriptomic data suggests that NRG1 can be used as a novel biomarker to predict patient prognosis when colorectal cancer and PSC coexist." (PMID 40432804, 2025). "Mesenchymal stem cells stimulated colorectal cancer invasion, survival, and tumorigenesis by releasing soluble NRG1." (PMID 40432804, 2025). "Remarkably, colorectal cancer and cholangiocarcinoma exhibited a relatively higher incidence of NRG1 fusion (0.22% and 0.33%, respectively)." (PMID 38173003, 2024). "By contrast, NRG1 was overexpressed in only 1% of colorectal cancers, a tumor type where anti-EGFR monoclonal antibodies (cetuximab and panitumumab) are currently approved for use." (PMID 28723928, 2017). "Recently report showed that MSCs stimulated invasion, survival and tumorigenesis of colorectal cancer cells through the release of soluble NRG1, activating the HER2/HER3-dependent PI3K/AKT signalling cascade in colorectal cancer cells." (PMID 26273429, 2015). "Intriguingly, unlike EGF and EREG, NRG1 failed to support the growth of pre-tumorigenic intestinal organoids lacking the tumor suppressor Apc, commonly mutated in human colorectal cancer (CRC)." (PMID 36912192, 2023). "Our result was consistent with the studies that bone marrow-derived MSCs (BM-MSCs) promoted colorectal cancer progression through paracrine neuregulin 1/HER3 signalling and tumor formation of multiple myeloma by cytokine IL-6 which was delivered via MSC-derived exosomes." (PMID 33744858, 2021). "In addition, NRG1 is involved in constitutive signalling by aberrant PI3K in cancer, CSNK1A1L in signalling by WNT in cancer, and MUCL1 in defective GALNT12 causes colorectal cancer." (PMID 31797963, 2019). "However this strategy may not be generally applied to cetuximab as NRG1 expression was markedly lower in colorectal cancer (CRC), another tumor type where cetuximab is an approved therapy and where EGFR signaling has been implicated." (PMID 28723928, 2017).